IL1B (interleukin 1 beta)
Diseases named in the same sentence as IL1B in open-access papers (continued):
Sharing a sentence is not in itself a finding about the gene and the disease.
cancer (continued). "It is not surprising that these functionally important polymorphisms in the IL-1B gene might be associated with cancer susceptibility." (PMID 23704929, 2013). "Stratification analyses of the IL-1B +3954C/T polymorphism on cancer susceptibility." (PMID 23704929, 2013). "Given the critical roles of IL-1β in inflammation and carcinogenesis, it is possible that both IL-1B −511C/T and +3954C/T polymorphisms may modulate the risk of cancer development." (PMID 23704929, 2013). "Association of the IL-1B –511C/T polymorphism with cancer susceptibility: Analyses of 81 case-control studies including 19547 cases and 23935 controls were conducted to explore the relationship between −511C/T and cancer risk." (PMID 23704929, 2013). "In addition, a polymorphism in exon 5 of IL1B(IL1B +3954C>T, rs1143634) has been found to affect IL1B gene expression and to be associated with occurrence of cancers." (PMID 23049925, 2012). "For IL1B+3954 polymorphism borderline significant risk association was observed for cancer risk." (PMID 23049925, 2012). "Stratification analyses of genetic susceptibility of IL1B+3954 polymorphism to cancer risk." (PMID 23049925, 2012). "Also, analyzed SNP in the IL-1β gene promoter (rs16944) affects IL-1β expression and is associated with increased risk of cancer and preterm birth." (PMID 22280494, 2012). "IL1B+3954 has a borderline significant association with increased cancer risk." (PMID 23049925, 2012). "In addition, a borderline significant association was observed between IL1B+3954 polymorphism and the increased cancer risk." (PMID 23049925, 2012). "Several studies have shown a link between polymorphisms in IL–1β, IL–6, IL–10 and cancer risk." (PMID 22567049, 2011). "In view of the roles of IL-1β played in cachexia, we postulated that its polymorphisms might have some association with the development of cancer cachexia." (PMID 17359523, 2007). "Interestingly, in the colon-26 murine model of cancer cachexia associated with systemic inflammation there appears to be a complex intratumoural amplification loop between IL-1β and IL-6, which can be downregulated by IL-10." (PMID 17088911, 2006). "Moreover, probiotic-derived metabolites such as indole derivatives and polyamines modulate inflammatory signaling by inhibiting NF-κB and reducing the production of pro-inflammatory cytokines like IL-6 and IL-1β, which are often elevated in cancer-associated inflammation." (PMID 40290037, 2025). "Consequently, IL-1β up-regulation is generally associated with poorer prognosis in cancer." (PMID 39475614, 2024). "One plausible explanation for why the A2A2 genotype might be linked to advanced CRC is that the A2 allele may interact with other genetic polymorphisms that increase IL-1β production, which plays a significant role in the inflammatory pathways involved in cancer progression." (PMID 39766795, 2024). "Additionally, single‐nucleotide polymorphism (SNP) in the promoter region within the IL‐1β gene may be involved in the expression level of IL‐1β and has been reported to be associated with various diseases including malignant tumors." (PMID 38798075, 2024). "Several hormones and cytokines, such as leptin, ghrelin, interleukin (IL)-1β, IL-6, and tumor necrosis factor alpha, contribute to the inflammation-mediated loss of fat and muscle and actively participate in the homeostasis of muscle and fat tissues in patients with cancer." (PMID 35203597, 2022). "IL-1β has been associated with the pathobiology of many diseases, such as familial periodic fever syndromes, multiple organ failure in sepsis, rheumatoid arthritis, type II diabetes, chronic obstructive pulmonary disease and growth, vascularization and metastasis of malignant tumors." (PMID 35048046, 2021). "Additionally, IL-1β may also serve as a pro-tumoral factor by inducing cancer angiogenesis and cancer-associated fibroblasts." (PMID 34150748, 2021).
cancer (continued). "Elinav and others defend that inflammation is causally related to some forms of cancer development, through processes that involve genotoxicity via the genotoxic activity of reactive oxygen produced by tissue macrophages and neutrophils, or through producing pro-inflammatory cytokines such as IL-1β." (PMID 31060614, 2019). "The present study therefore aims to investigate risk factors for ICC and inflammation-linked cancer, and focus on opisthorchiasis and polymorphisms in proinflammatory cytokines (IL-1β and TNF-α) to assess whether these genes are involved in opisthorchiasis-related ICC risk." (PMID 30139338, 2018). "The existence of the INS/IL-1α motif in pINSd and IL-1α and its absence in IL-1β could account for the unique activity of IL-1α in cellular metabolism associated with cell growth and cancer that diverges from IL-1β activity, which is limited to inflammatory functions." (PMID 27226621, 2016). "In addition, IL1β polymorphisms were reported to be associated with an increased risk of cancer." (PMID 25483140, 2015). "However, it remains unclear how IL-1β may contribute to the initiation and development of these inflammation-associated cancers." (PMID 23174018, 2012). "IL-1β-IL-1R1 signaling is required for IEC SIRT3 deficiency-induced TH1 and CTL differentiation in cancer." (PMID 41487042, 2026). "The reduction in IL‐1β and F4/80 expression following metformin treatment has been reported in cancer models, indicating the importance of AMPK in metformin's anti‐inflammatory effects." (PMID 41346233, 2026). "Currently, the effectiveness of IL-1β inhibitors in cancer treatment is still being evaluated in clinical trial phase." (PMID 41145465, 2025). "IL-1b is pro-tumoral, having been shown to be upregulated in many solid tumors, promoting cancer progression." (PMID 40075580, 2025). "Cancer cells also secrete proinflammatory cytokines, such as interleukin-1 beta (IL-1β), tumor necrosis factor-alpha (TNF-α), and vascular endothelial growth factor (VEGF), which foment a pro-thrombotic environment in the blood." (PMID 41040779, 2025). "Herein, we discuss the importance of IL-1β derived from cancer cells which impacts primary tumors, particularly metastatic lesions, separately from and in addition to its more recognized role in immune-mediated inflammatory events." (PMID 39858071, 2025). "Although IL-1β is widely known as a cancer-promoting cytokine, the IL-1β-mediated inflammatory response has also been shown to suppress metastatic colonization, and IL-1β blockade promotes metastasis, although it reduces primary tumor growth." (PMID 40562870, 2025). "Based on this evidence, we demonstrated that NSCLC TEVs were able to increase cancer cell migration and that this effect was amplified by IL-1β stimulation." (PMID 40725070, 2025). "Several cytokines (e.g., interleukin (IL)-8, IL-6, IL-1β) that are elevated in persons with COPD have been previously associated with LC risk (including LCINS) and are important for LC and/or cancer biology." (PMID 40456733, 2025). "In conclusion, CAS cells and IL‐1β+ macrophages play pivotal roles in the progression from preinvasive to invasive LUADs, positioning them as promising targets for cancer prevention and reversion strategies." (PMID 40824728, 2025). "Exosomes derived from immune cells, epithelial cells, and cancer cells have been shown to enhance inflammasome activation, triggering the release of pro-inflammatory cytokines such as IL-1β and IL-18." (PMID 40141358, 2025). "We observed that MyD88, p-ERK, p-NF-kB, TNF-α, IL-1β, and IL-6 were significantly suppressed in cancer cells treated with SsnB compared to the control groups." (PMID 40143078, 2025).
cancer (continued). "This CXCL1/CXCR2 axis in CAFs mediates cancer cell invasion via induction of IL-1β, revealing a reciprocal dependency between CAFs and cancer cells within the OSCC microenvironment." (PMID 41445742, 2025). "Confocal microscopy observations showed an altered cell morphology with elongated and enlarged cells after 48 and 72 h of treatment with TGF‐β2/IL‐1β or each cancer cell CM compared to the control condition." (PMID 40028673, 2025). "These also de-repress IL-1β in cancer cells expressing the AR, which are otherwise unable to produce this cytokine." (PMID 39858071, 2025). "BBG can reduce inflammation and alleviate cancer pain by inhibiting glial cell activation and blocking the release of IL-1β and IL-18." (PMID 40717979, 2025). "In the current study, our results show that IL-1β downregulates the expression of different caspases like caspase-8 and caspase-3, favoring cancer cell survival." (PMID 40725140, 2025). "In recent years, many basic and translational studies have investigated the development and use of novel IL-1β blockers in cancer therapy." (PMID 40593461, 2025). "One logical explanation is that IL-1β contributes to the development of an inflammatory tumor microenvironment, promoting carcinogenesis in various types of cancer." (PMID 40079000, 2025). "IL-1β is only expressed by a small number of cell types, including macrophages, and has been identified as a promoter of glycolysis in multiple cancer types." (PMID 39838454, 2025). "Paradoxically, NF-κB also mediates early proinflammatory responses in TAMs via cytokines such as IL-1β and IL-6, which fuel tumorigenesis by promoting cancer cell survival and proliferation." (PMID 40562870, 2025). "Both IL-1β and TNFα have been shown to promote cancer progression through cell proliferation, migration, and metastasis." (PMID 40381373, 2025). "Supporting this, mice with overexpressed IL-1β in the stomach develop spontaneous gastric inflammation and cancer." (PMID 40141358, 2025). "Following the accumulated findings of IL-1β’s central modulatory role in the immune system and the implication of inflammatory pathways in cancer, the use of IL-1β antagonists was first proposed and then also pursued for oncology disorders." (PMID 39858071, 2025). "Recent advances have highlighted the potential of targeting inflammasome components such as sensor proteins (e.g., NLRP3, AIM2), adaptor proteins (e.g., ASC), caspase-1, and downstream cytokines IL-1β and IL-18—to modulate the immune response against cancer." (PMID 40155968, 2025). "Specifically, cytokines like TNF-α, IL-6, IL-18, IL-1β, and INF-γ are implicated in cancer cachexia, promoting elevated energy expenditure, reduced appetite, and skeletal muscle degradation." (PMID 39996717, 2025). "All these events clearly illustrate the seminal role of IL-1β in cancer cell proliferation and metastasis." (PMID 40725140, 2025). "Microglial and astrocytic activation, along with p38 MAPK, IL-18, and IL-1β signaling, play critical roles in the development of pathological pain induced by nerve injury, cancer, and inflammation in male animals." (PMID 41511304, 2025). "Our findings also highlight the role of IL-1β in activating autophagy mechanisms that are extremely beneficial in facilitating clearance of metabolic waste, thus allowing swift growth of cancer cells." (PMID 40725140, 2025). "Among the various pro-inflammatory cytokines, Interleukin-1 beta (IL-1β) plays a central role in linking inflammation to cancer, due to its elevated levels in a wide range of malignancies." (PMID 40725070, 2025). "Among the pro-inflammatory cytokines, IL-1β, IL-6, and IL-12 showed the most robust differences, with IL-1β showing a maximum plasma concentration of 182 pg/mL in cancer patients, compared to 3 pg/mL in controls." (PMID 40612845, 2025).
cancer (continued). "Chronic inflammation is a known regulator of EMT, including the presence of cytokines like IL-1β in cancer." (PMID 39858071, 2025). "It is rich in tumor necrosis factor α (TNF-α), IL-1β, IL-6, and other chemokines and cytokines, which stimulate cancer cell growth, promote the formation of blood vessels, and reshape the extracellular matrix." (PMID 40244135, 2025). "In contrast, IL-1β has been extensively studied as a pro-tumor factor, exhibiting oncogenic effects in various cancers." (PMID 39744568, 2025). "During early stage in tumor progression, secreted cytokines from cancer cells, such as IL-1β, guide normal fibroblasts to differentiate into proinflammatory CAFs depending on NF-κB activation." (PMID 40707476, 2025). "Various cytokines such as TNF-a, TGF-b, IL-10, IL-1b, and IL-6 are involved in the crosstalk between cancer initiation/progression and sleep–wake cycles." (PMID 40075580, 2025). "This occurs through IL-1β/IL-1R1 signaling, which is activated under hypoxic conditions and drives aggressive behavior in triple-negative BC (TNBC) and cancer-associated fibroblasts." (PMID 41150737, 2025). "Recent evidence highlights the role of inflammasomes in cancer development and progression, with particular emphasis on the downstream effector cytokine IL-1β." (PMID 40155968, 2025). "Cancer cells develop resistance to drugs through a complex process involving crucial contributors like nuclear factor‐κB (NF‐κB) and IL‐1β." (PMID 40237399, 2025). "As previously noted, IL-1β plays a role in the inflammatory interaction between cancer cells and macrophages." (PMID 40861469, 2025). "IL-1B was found to be significantly elevated in the mice model of adenomatous polyposis coli (APC) cancer." (PMID 40868987, 2025). "While this is considered a pro-inflammatory macrophage gene in healthy contexts, the net effect of TAM expression of IL-1β is decreased immune response efficacy, treatment resistance, and disease recurrence in cancer." (PMID 41445746, 2025). "Inflammation has always been an integral part of the HCC disease biology, and the expression of IL-6, IL-8, and IL-1B have all been shown to promote cancer cell stemness by reducing self-renewal pathways." (PMID 41283329, 2025). "Our present results clearly support a role for IL-1β in enhancing autophagy and thereby aiding cancer metastasis." (PMID 40725140, 2025). "Both IL-6 and IL-1b illustrate how the sleep–wake cycle is connected to cytokines that play a role in cancer initiation/progression and how the disruption of the cycle is potentially a risk factor for tumorigenesis." (PMID 40075580, 2025). "Prostate cancer is characterized by high levels of IL-1β, IL-18, IL-6, and MIC-1/GDF-15 that are clinically relevant for this association with the risk of carcinoma and the prognosis of established cancer." (PMID 41560727, 2025). "By releasing IL‐1β, OSCC cells enhance tube formation capacity of LECs via IL‐1β directly binding to IL‐1R‐1 in LECs, suggesting the potentials of IL‐1β/IL‐1R‐1 axis in promoting cancer‐related lymphangiogenesis and LN metastasis of OSCC." (PMID 40135589, 2025). "The results showed that the expression levels of CD3, CD4, CD8, CD20 and IL-1β in the cancer nest were all increased after two recurrences, indicating that the immune cell infiltration was increased and the immune microenvironment was effectively activated." (PMID 40661951, 2025). "Due to its ability to stimulate angiogenesis, IL-1β has also been shown to contribute to the metastasis of cancer cells, indicating its pro-tumorigenic nature." (PMID 41561739, 2025). "Previous studies have shown that autophagy promotes the secretion of protumorigenic factors—including IL-6, IL-8 and MMP2—in Ras-driven cancers and facilitates IL-1β secretion through unconventional secretory pathways." (PMID 41408407, 2025).
cancer (continued). "First, regarding cytokines in AF, the prognostic impact of inflammatory cytokines in patients with malignant tumors has been investigated in a study that reported the presence of IL-1β, IL-6, IL-8, IL-12, TNF-α, and IL-10 in AF." (PMID 39755760, 2025). "These proinflammatory cytokines include IL-1β, which has been reported to be overexpressed in several cancers and shown to activate several signalling pathways." (PMID 41595577, 2025). "Conversely, ABCB5 demonstrates a strong association with chemoresistance and immune suppression, driven by its role in regulating cancer stemness and IL-1β/IL-8/CXCR1 signaling loops." (PMID 40445912, 2025). "The inflammatory cytokines secreted by leukocytes, such as TNF-α, IL-6, and IL-1β, promote cancer cell proliferation, survival, and resistance to apoptosis." (PMID 39869563, 2025). "Anti-IL-1β monoclonal antibodies (mAbs) can boost the efficacy of PD-L1 inhibition in some types of cancer." (PMID 40165901, 2025). "In conclusion, the interplay between these inflammatory mediators—IL-6, IL-1β, TNF-α, CCL2, PGE2, GM-CSF, and bradykinin—highlights their collective role in the mechanisms underlying cancer pain." (PMID 40579593, 2025). "Inflammatory cytokines such as NF-κB, IL-6, IL-1β, and TNF-α are indicators of inflammation and can be used to assess the severity of cancer-associated myocardial damage." (PMID 40182041, 2025). "Recent findings indicate that IL-1β exacerbates myocardial injury in cancer patients receiving chemotherapy and immune checkpoint inhibitors." (PMID 40697377, 2025). "For instance, a longitudinal study illustrated that increased sleep duration or decreased SD were associated with the attenuation of pro-inflammatory biomarkers (such as IL-1β and IL-6) and the counter-regulatory cytokine (IL-10) among cancer survivors." (PMID 41470834, 2025). "In cancer cells and aggressive tumors, IL-1B usually stimulates angiogenesis, immune cell proliferation, and invasion." (PMID 40868987, 2025). "The abundant production of 1O2 significantly activates caspase‐3, inducing the release of N‐GSDME, which subsequently triggers pyroptosis in cancer cells and the release of pro‐inflammatory cytokines IL‐1β and IL‐18." (PMID 41117183, 2025). "Third, previous research suggests the release of interleukins (IL-1β) in the immune system potentially facilitates the growth and invasion of tumors by stimulating the self-renewal of Cancer Stem Cells (CSC) and EMT." (PMID 40019680, 2025). "IL-1β, a factor secreted by various cells, has pleiotropic effects on immune cells, angiogenesis, cancer cell proliferation, migration and metastasis." (PMID 40948749, 2025). "Another factor secreted by CAF in contrast to normal fibroblasts is IL‐1β, known to affect cancer cell invasion." (PMID 40255916, 2025). "Macrophages and neutrophils primarily contribute to the synthesis of TNFα, which subsequently stimulates the production of other proinflammatory cytokines, including IL-6 and IL-1β, thus promoting cancer." (PMID 40869207, 2025). "Specifically, IL-1β, NF-κB1 and TNF have all been associated with promoting an inflammatory microenvironment in cancer settings leading to proliferation, angiogenesis, and cell survival, whilst also being linked with specific cell death mechanisms." (PMID 40956832, 2025). "Future studies should compare the impact of acute exercise on IL1B gene and protein expression in different leukocyte populations and types of cancers, as well as long-term exercise interventions, to reveal the clinical implications of these findings." (PMID 40881686, 2025). "Tolcapone at 20 μM inhibited 50% of U87 cell growth, and IL-1RA at 1 μg/mL resulted in a 51% decrease in the IL-1β-induced cancer cell growth in human glioblastoma cancer." (PMID 40725140, 2025). "In this regard, chemotherapy can stimulate cancer cells to secrete IL-1β, which induces neutrophil extracellular trap (NET) formation, and specific NET-associated proteins are related to chemoresistance." (PMID 41155372, 2025).